STAT3 (signal transducer and activator of transcription 3)
Diseases named in the same sentence as STAT3 in open-access papers (continued):
Sharing a sentence is not in itself a finding about the gene and the disease.
pancreatic cancer (continued). "Future studies should focus on whether silencing of STAT3 expression using STAT3 shRNA or its inhibitor such as non-receptor tyrosine kinase is useful as a novel adjuvant therapy to chemotherapy for pancreatic cancer patients." (PMID 21991388, 2011). "Targeting of Stat3 activation may prove to be a more effective approach to controlling invasion than merely targeting individual molecules, such as VEGF and MMP-2, possibly representing a novel approach to regulating pancreatic cancer invasion." (PMID 20482858, 2010). "However, STAT3 was found to be necessary for the development of the acinar-to-ductal metaplasia process, an early event in PDA pathogenesis, which is mediated by ectopic expression of the Pdx1 transcription factor, a key regulator in early pancreatic cancer development." (PMID 38326371, 2024). "Moreover, the orally available direct STAT3 inhibitor napabucasin (BBI608) was approved by the United States Food and Drug Administration (FDA) for the treatment of two cancers, including gastric/gastroesophageal junction (GEJ) cancer and pancreatic cancer in 2016." (PMID 35356799, 2022). "In pancreatic cancer, LB-1 decreased the activity of HIF-1α via inhibiting its upstream pathway PI3K/Akt/mTOR, moreover, LB-1 could inhibit the connection between HIF-1α, p-STAT3 and p300, repressing VEGF expression, in addition, LB-1 accelerated HIF-1α degradation by ubiquitin–proteasome pathway." (PMID 32587480, 2020). "Finally, we showed that NOS inhibitor effectively repressed STAT3 S-nitrosylation in PANC-1 cells, which induced great alteration of STAT3 phosphorylation and PANC-1 cell viability, indicative of the regulatory roles of protein S-nitrosylation in pancreatic cancer development." (PMID 31801946, 2019). "Nevertheless, the difference between STAT3 target gene expression between pancreatic tumor tissue and cell lines was not substantial, which suggests that some targets might be mainly regulated by STAT3 in tumor cells, while others are mainly regulated in non-tumor cells." (PMID 31796877, 2019). "However, the STAT3 phosphorylation and its downstream targeted genes expression in tumor tissue were not determined, so that STAT3 signaling pathway whether acted as the key molecular target of Xn in pancreatic cancer pending further study." (PMID 29872398, 2018). "Although the activation of inflammatory signals by NTS has not been documented in pancreatic cancer, our RNA‐seq analysis showed that NTS activates the NF‐κB and STAT3 inflammatory signaling pathways." (PMID 33034134, 2021). "IL-37 expression was decreased in pancreatic cancer, down-regulated IL-37-mediated gemcitabine resistance via interacting with HIF-1α and signal transducer and activator of transcription 3 (STAT3) and forming the HIF-1α/IL-37/STAT3 negative feedback." (PMID 32587480, 2020). "Further, EGFR knockdown showed that pSTAT3 levels were lower in EGFR-shRNA pancreatic cancer cells compared to NTC-shRNA control cells without altering total protein levels, suggesting that STAT3 phosphorylation is partly dependent on EGFR protein levels." (PMID 29262554, 2017). "Overexpression of ZIP4 may cause activated IL-6/STAT3 pathway and also led to increased VEGF and MMP expression, however, the detailed mechanism of how ZIP4 overexpression causes the activation of the downstream signalling pathways to promote pancreatic cancer growth is not clear." (PMID 23857777, 2013). "For example, HMGA2 mediated the occurrence of triple-negative breast cancer by activating the NF-kB/IL-6/IL-8/STAT3 axis; HMGA2 activated the mTOR signaling pathway to inhibit ferroptosis, thereby enhancing the death resistance of pancreatic cancer and reducing chemotherapy sensitivity." (PMID 40703517, 2025). "In summary, CDK1 and STAT3, which are highly expressed in PDAC and PCSCs, are negatively correlated with the survival of PDAC patients and play an important role in maintaining pancreatic cancer stemness." (PMID 37743465, 2023).
pancreatic cancer (continued). "This indicated that STAT3 activity, rather than just STAT3 mRNA, might be altered in the TME of pancreatic cancer." (PMID 31796877, 2019). "Our previous study has shown that bazedoxifene is capable of blocking the IL6/GP130/STAT3 signaling pathway by inhibiting IL6‐induced homodimerization of GP130, leading to a potential antitumor effect, which has been demonstrated in triple‐negative breast cancer and pancreatic cancer." (PMID 39152779, 2024). "Our study showed that EPA treatment inhibited cell visibility and p-STAT3, HPS, and ACC-1, but not FASN expressions in KRAS-mutant SUIT-2 cells, suggesting that EPA treatment might reduce ACC-1-mediated de novo lipogenesis to downregulate the tumor growth and survival of pancreatic cancer cells." (PMID 33801246, 2021).
ovarian carcinoma (611 papers, 2005 to 2026). A malignant neoplasm originating from the surface ovarian epithelium. "In another study, PIK3R1 copy number loss or reduced PIK3R1 expression rendered ovarian cancer cells vulnerable to the inhibition of AKT or JAK2/STAT3 inhibitors." (PMID 39858051, 2025). "MDMs have been shown to promote ovarian cancer cell survival by activating the STAT3 signaling pathway, whereas TRMs have been associated with ovarian cancer cell proliferation and invasion of the metastatic niches at the peritoneal cavity and omentum." (PMID 38411356, 2024). "The JAK/STAT3 pathway is also activated and associated with tumor progression and poor prognosis in patients with ovarian cancer, and is a potential target for new therapeutic agents." (PMID 37444425, 2023). "Consistently, GANAB overexpression has the potential to reverse the reduced ovarian cancer cell proliferation, migration, and invasion ability induced by STAT3 deficiency." (PMID 37781028, 2023). "Studies have shown that high STAT3 activity or phosphorylated STAT3 activation is associated with poor overall survival and unfavorable progression-free survival in ovarian cancer patients." (PMID 37465088, 2023). "Stromal overexpression of CXCL14 in ovarian cancer was linked to poor patient survival via STAT3-dependent manner due to increased tumor cell proliferation." (PMID 36868311, 2023). "STAT3 is implicated in several proliferation and apoptosis signaling axes and is often aberrantly activated in ovarian cancer." (PMID 35326569, 2022). "Cisplatin resistance in ovarian cancer cells has been associated with an increased phospho-STAT3 expression; conversely, both JAK2 and STAT3 inhibitors can enhance cisplatin sensitivity." (PMID 35269562, 2022). "The overactivation of IL-6 pathways, particularly activation of STAT3, has been implicated in the aggressiveness of ovarian cancer." (PMID 36429126, 2022). "In human ovarian cancer and glioma cancer, tumor-associated Tregs trigger macrophages to secrete IL-10 and IL-6, which activate STAT3 and induce B7-H4 transcription." (PMID 35410218, 2022). "Here, we show that PARPi treatment promotes STAT3 activation in ovarian cancer cells, tumor-associated immune cells and fibroblasts, resulting in PARPi resistance and immunosuppression." (PMID 34956861, 2021). "Ovarian carcinoma-associated mesenchymal stem cells can activate the tumor cell stemness via activating IL6/STAT3 signaling." (PMID 33768003, 2021). "STAT3 also interacting with miRNA-92 promoted malignant progression in ovarian cancer, and the potential mechanism was associated with regulation of the Wnt signaling pathway." (PMID 34539736, 2021). "Our findings collectively indicate that in germline BRCA ovarian cancer patients, PARPi treatments significantly elevate STAT3 activity in tumor cells and tumor-associated immune cells, including B cells, CD4+ and CD8+ T cells, and CAFs." (PMID 34956861, 2021). "Our prior work demonstrated increased p-STAT3 positive B cell infiltration in omental tissue, and it is associated with poor survival of ovarian cancer patients." (PMID 34956861, 2021). "Elevated expression of STAT3 was often observed in the serum and ascites fluid of ovarian cancer patients, and was associated with a poor clinical outcome." (PMID 34369236, 2021). "For the first time, our studies showed increased STAT3 activation in tumor cells, tumor-associated immune cells, and CAFs in tumor biopsies from ovarian cancer patients that progressed following PARPi treatment." (PMID 34956861, 2021). "Our studies show that the acquisition of Olaparib resistance in both BRCA-wildtype and BRCA2-mutated ovarian cancer cells is accompanied by increased STAT3 activity and pro-tumorigenic gene expression." (PMID 34956861, 2021). "We conducted a systematic review and meta-analyses to clarify the associations between STAT3/p-STAT3 expression and clinicopathologic characteristics and prognostic factors of ovarian cancer." (PMID 34789292, 2021).
ovarian carcinoma (continued). "The introduction of AGTR1 knockdown reversed the promotion effect of miR-140-3p inhibitor on the activation of MEK/ERK/STAT3 pathway in ovarian cancer cells, indicating the loss of AGTR1 expression can result in the inhibition of ovarian cancer progression." (PMID 34496800, 2021). "Among the included studies, 13 investigated the association between clinicopathological parameters and STAT3/p-STAT3 expression in ovarian cancer patients." (PMID 34789292, 2021). "Our previous studies also showed that increased B cell infiltration and p-STAT3 expression in omental tissue are associated with poor survival in ovarian cancer patients." (PMID 33335857, 2020). "STAT3 knockdown with specific small interfering RNA causes a loss of cell growth and induces apoptosis in human ovarian cancer cells, consistent with down-regulation of cyclin D1 and survivin level." (PMID 31949487, 2020). "In support, STAT3 inhibition has been found to be associated with a mdr1 mRNA down-regulation in ovarian cancer cells." (PMID 31963614, 2020). "As with CD44, STAT3 signaling has been frequently implicated in ovarian cancer metastasis, therapy resistance, and CSC maintenance." (PMID 33335857, 2020). "Jiang B reported that miR-217 inhibited tumor-induced M2 macrophage polarization by targeting IL-6 and regulating the JAK3/STAT3 signaling pathway, probably providing an underlying therapeutic target in the treatment of ovarian cancer." (PMID 33392180, 2020). "Nuclear existence of activated (phosphorylated) STAT3 has been observed in 70% of advanced-stage ovarian cancer and that has been associated with decreased survival." (PMID 33023532, 2020). "Aberrant activity of STAT3 plays a critical role in ovarian carcinogenesis and is associated with poor prognosis for ovarian cancer patients." (PMID 30755611, 2019). "Our data demonstrate that STAT3 expression is tightly associated with tumor proliferation and aggressiveness in both in vitro and in vivo ovarian cancer models." (PMID 31534498, 2019). "STAT3 deletion causes remarkable tumor growth inhibition in several tumor xenograft models of ovarian cancer." (PMID 31534498, 2019). "In ovarian cancers, STAT3 over-activation has been associated with a reduced platinum response and poor prognosis." (PMID 31766284, 2019). "Collectively, our findings indicate that loss of STAT3 in ovarian cancer cells alters stem like properties." (PMID 31534498, 2019). "It has been documented that Sal induces apoptosis in NCI/ADR-RES, DXR, and OVCAR-8 ovarian cancer cells via downregulation of S-phase kinase-associated protein-2 (Skp-2) and signal transducer and activator of transcription 3 (Stat3) inactivation." (PMID 29433536, 2018). "Increased levels of phosphorylated STAT3 are associated with chemoresistance in ovarian cancer cells, with STAT3 knockdown facilitating apoptosis induced by cisplatin." (PMID 30487436, 2018). "STAT3 is constitutively activated in ovarian cancer and its continued activation is associated with tumor progression and poor prognosis in ovarian cancer patients." (PMID 29986501, 2018). "Intriguingly, our study shows a null association between STAT3 mRNA expression and OS of ovarian cancer patients." (PMID 28536310, 2017). "Previous studies have demonstrated that p-STAT3 was associated with poor survival in ovarian cancer." (PMID 28536310, 2017). "Resveratrol inhibits STAT3 activation and causes remarkable growth arrest and cell death of ovarian cancer (OC) cells." (PMID 27551495, 2016). "Recently, it was reported that aberrant activation of the STAT3 pathway is found in more than 70% of ovarian cancers and was associated with decreased OS." (PMID 27855669, 2016). "Here, we provide the first indication that Par3 is associated with ovarian cancer progression through the IL-6/STAT3 pathway." (PMID 27855669, 2016).
ovarian carcinoma (continued). "Induction of STAT3 signaling was associated with enhanced chemoresistance of cancer cells, while a STAT3 inhibitor was able to enhance chemosensitivity in epithelial ovarian cancer cells." (PMID 25638155, 2015). "The STAT3 pathway responded early to platinum drugs associated with cisplatin resistance in epithelial ovarian cancer." (PMID 25006835, 2014). "Coupling of the stem cell marker CD44 with the embryonic stem cell marker Nanog has been shown to be associated with the activation of STAT3 in ovarian cancer cells." (PMID 24782986, 2014). "We have recently shown enhanced secretion of interleukin-6 (IL-6) and G-CSF and activation of associated downstream STAT3 pathway in several ovarian cancer cell lines in response to cisplatin or paclitaxel treatments in vitro." (PMID 24782986, 2014). "It has been shown that the phosphorylation and translocation of STAT3 to the nucleus are frequent events in ovarian carcinoma that are associated with poor prognosis." (PMID 23593315, 2013). "In cancer, STAT3 has been implicated in EGF-mediated EMT in ovarian cancer cell lines and STAT1 has been reported to inhibit angiogenesis in murine fibrosarcoma tumor cells." (PMID 24274066, 2013). "The association between STAT3 activation and migratory phenotype of ovarian cancer cells was investigated by EGF-induced epithelial–mesenchymal transition (EMT) in OVCA 433 and SKOV3 ovarian cancer cell lines." (PMID 19088723, 2009). "Similarly, PDLIM4 is associated with poor prognosis in ovarian cancer by inhibiting tumor invasion through the suppression of STAT3 signaling." (PMID 40243891, 2025). "Notably, the PDLIM family comprises 10 members, several of which—including PDLIM250 and PDLIM4—have been linked to ovarian cancer progression via mechanisms such as the STAT3 signalling pathway." (PMID 40697100, 2025). "Mechanistically, curcumin inhibited the NF‐κB and STAT3 pathways, activated antioxidant signaling, and reduced mutations in Ras family oncogenes, supporting its role as a preventive and therapeutic agent in ovarian cancer." (PMID 41323836, 2025). "Among these, hypoxia and STAT3 signaling are enhanced in ECs from patients with PAH and repress RAB7 expression in ovarian cancer cells, suggesting that hypoxia and STAT3 signaling may contribute to RAB7 deficiency in ECs from patients with PAH." (PMID 38015641, 2024). "It has been reported that the loss of PIK3R1 could activate AKT and STAT3 signaling in ovarian cancer." (PMID 37781028, 2023). "Apart from its role in inflammation, Stat3 signaling has also been linked to a cancer stem cell phenotype in the context of another syndecan member, syndecan-1, and to a cancer stem cell phenotype and resistance to chemotherapy in ovarian cancer." (PMID 35628603, 2022). "A study demonstrated that the feedback activation of STAT3 might be the mechanism underlying EGFR inhibitor resistance in ovarian cancer." (PMID 34369236, 2021). "The authors of this preclinical study demonstrated that high levels of IL-6 contained in the ADSC-conditioned medium activated the STAT3 pathway, which is linked with the promotion of tumor growth and invasion and is responsible for the increase in autophagy in ovarian cancer cells." (PMID 34440886, 2021). "In hypoxic ovarian cancer cells, FV-429 can interfere with the expression and phosphorylation of c-Scr, inhibit the translocation and DNA binding activity of STAT3, and inhibit HIF-1α expression, causing the downregulation of HK2 and VEGF and enhancement of the G2/M arrest induced by paclitaxel." (PMID 35004308, 2021). "Moreover, since aberrantly activated STAT3 is strongly associated with chemoresistance CA also enhances cytotoxicity of chemotherapeutic drugs to ovarian cancer cells via inhibition of STAT3 activation." (PMID 31949487, 2020). "The ability of both CD44 and STAT3 to activate HIF-1α associated pathways may suggest their concomitant impact on glucose metabolism during ovarian cancer progression." (PMID 33335857, 2020).